CD163 (CD163 molecule)
Diseases named in the same sentence as CD163 in open-access papers (continued):
Sharing a sentence is not in itself a finding about the gene and the disease.
cutaneous melanoma (15 papers, 2016 to 2025). A primary melanoma arising from atypical melanocytes in the skin. "The results of this study demonstrate a clear increase in both CD68+ and CD163+ macrophage infiltration in cutaneous melanoma tissues as tumor thickness and stage progress." (PMID 41007741, 2025). "This study aimed to quantitatively assess CD68+ and CD163+ macrophages in the intratumoral and peritumoral stroma of cutaneous melanoma at different stages of the disease." (PMID 41007741, 2025). "Immunohistochemical staining revealed the presence of CD68+ and CD163+ macrophages in both intratumoral and peritumoral compartments of cutaneous melanoma samples." (PMID 41007741, 2025). "In our previous study, high CD163 expression was associated with lower OS, suggesting the prognostic significance of CD163 expression in cutaneous melanoma." (PMID 32756500, 2020). "Recent studies in advanced cutaneous melanoma also revealed that increased serum levels of CD163 were related to positive response to anti-PD-1 antibody." (PMID 32756500, 2020). "This study aims to address this gap by providing a comprehensive analysis of CD68+ and CD163+ macrophages in cutaneous melanoma stages I–III, which may be critical for elucidating the mechanisms of tumor progression." (PMID 41007741, 2025). "In addition, the spatial transcription data on SpatialDB showed that RAB5B spatially overlapped with endothelial cell markers PECAM1 and VWF in BCC cancer tissues and M2 macrophage markers CD68 and CD163 in skin melanoma tissues." (PMID 40842984, 2025). "Interestingly, in 2018, a previous report showed that soluble CD163 expression in serum was significantly increased in advanced cutaneous melanoma patients who were responders to the nivolumab immunotherapy." (PMID 39015503, 2024). "This suggests that PD-1 and LAG-3 expression could be affected by CD163-positive TAMs in cutaneous melanoma." (PMID 32756500, 2020). "Our results may support combinatory immunotherapeutic strategies, especially for targeting anti-PD-1 and/or anti-LAG-3 with anti-CD163 or macrophage inhibitors in advanced cutaneous melanoma." (PMID 32756500, 2020). "As previously reported, increased levels of soluble(s) CD163 at 6 weeks could predict the efficacy of nivolumab monotherapy 2–3 months after its first administration for the treatment of advanced cutaneous melanoma." (PMID 31080803, 2019). "Despite significant progress in understanding the role of macrophages in cutaneous melanoma, the quantitative characteristics of CD68+ and CD163+ cells at different stages of the disease remain insufficiently studied." (PMID 41007741, 2025). "Furthermore, high serum levels of soluble CD163 were found to be associated with worse clinical outcome in metastatic RCC; its measurement during treatment with anti PD-1 therapy seems to play a predictive role of effectiveness in patients with advanced cutaneous melanoma." (PMID 38740647, 2024). "The median number of CD163+cells/HPF was 64.25 (IQR = 42.5–84.35) and showed a statistically significant difference among the four diagnosis groups (oral melanoma, cutaneous melanoma, cutaneous melanocytoma and oral melanocytoma; p < 0.001)." (PMID 35937296, 2022). "An analysis of macrophage infiltration in cutaneous melanoma based on tumor thickness according to the Breslow scale revealed a clear trend toward an increase in both intratumoral and peritumoral numbers of CD68+ and CD163+ macrophages with tumor progression." (PMID 41007741, 2025). "Oral melanomas were characterized by the highest number of CD163+cells/HPF (Mdn = 73.9; IQR = 54.5–108.9), followed by cutaneous melanomas (Mdn = 64.9; IQR = 51.7–83.36), cutaneous melanocytomas (Mdn = 49.6; IQR = 41.1–64.35), and oral melanocytomas (Mdn = 17.4; IQR = 8.1–25.95)." (PMID 35937296, 2022). "Serum levels of soluble CD163 were increased after 6 weeks in responders compared to non-responders after initial treatment for cutaneous melanoma." (PMID 31192215, 2019).
cutaneous melanoma (continued). "The number of CD163+, CD204+, and MAC387+ cells was significantly higher in oral melanomas compared to oral melanocytomas (p < 0.001; p < 0.05 and p < 0.01, respectively), whereas Iba1 was differentially expressed in cutaneous melanomas and melanocytomas (p < 0.05)." (PMID 35937296, 2022). "The lack of statistical significance evidenced between cutaneous melanomas and cutaneous melanocytomas for CD163, CD204 and MAC387 expression, may reflect the unpredictable behavior of the first group of tumors." (PMID 35937296, 2022). "However, also the relationship between the expression of CD163 and LAG-3 in cutaneous melanoma has not yet been investigated." (PMID 32756500, 2020).
dengue (15 papers, 2014 to 2025). "Markers of MAS/hyperinflammation including high levels of ferritin, triglycerides, and soluble CD163 (sCD163) have been demonstrated in dengue and are associated with disease severity." (PMID 35267010, 2022). "Dengue-infected patients also had decreased monocyte-associated CD163 compared with healthy controls, consistent with the increase in sCD163 observed in their serum." (PMID 30666927, 2019). "A study of virus-inclusive scRNA-Seq revealed that CD163 was expressed in monocytes only in subjects who subsequently developed severe dengue." (PMID 36091000, 2022). "Here, we investigated the sensitivity of the 3D Stack in detecting a severe dengue biomarker—soluble CD163 (sCD163)—within the serum matrix." (PMID 34945351, 2021). "Soluble CD163 which is a marker of macrophage activation syndrome has been previously shown to differentiate those who have severe dengue from DF." (PMID 33194836, 2020). "IFITI and CD163 expression in CD14+CD16+ monocytes, was shown to precede the development of severe dengue." (PMID 33194836, 2020).
Hypertension (15 papers, 2013 to 2025). The presence of chronic increased pressure in the systemic arterial system. "Urinary CD163 levels were retrospectively measured by enzyme-linked immunosorbent assay (ELISA) in 51 patients with systemic vasculitis, 42 essential hypertensions, and 36 healthy volunteers." (PMID 33997033, 2021). "Moreover, our results indicated a strong association between CD163 and hypertension, consistent with results from previous studies." (PMID 37974098, 2023). "It suggested that there were differences in the cells and cytokines involved in the process of vascular injury caused by vasculitis and hypertension, and CD163 may be a relatively specific indicator of vasculitis." (PMID 33997033, 2021). "Studies in a rat model of hypertension found that CD163+ macrophage accumulation in the mesenteric artery adventitia is linked to increased blood pressure through macrophage-derived oxidate stress acting on ganglionic neuronal alpha-2 adrenergic receptors." (PMID 37342800, 2023). "Our results revealed the existence of a distinct group of microglial cells expressing specific surface markers (CD86, CD11b/c, and CD163) only in early hypertension, represented by cluster 3 (C3)." (PMID 38115109, 2023). "Secondly, it is also the first time that urinary CD163 has been compared between vasculitis and hypertension." (PMID 33997033, 2021). "Urinary CD163 levels were significantly higher in patients with systemic vasculitis [68.20 (38.25~158.78) (pg/ml)] compared to essential hypertension [43.86 (23.30-60.71) (pg/ml)] (p = 0.003) and the healthy volunteers [30.76 (9.30-54.16) (pg/ml)] (p < 0.001)." (PMID 33997033, 2021). "The results showed that the urinary CD163 levels in vasculitis group were higher than essential hypertension." (PMID 33997033, 2021). "Therefore, in order to exclude the influence of the factors, we also compared and analyzed urinary CD163 levels in the vasculitis group and essential hypertension group." (PMID 33997033, 2021). "In addition to being secreted by monocytes, CD163 can also be secreted by other immune cells such as endothelial cells, and our patients with vasculitis often have high blood pressure." (PMID 33997033, 2021). "Urinary CD163 levels were significantly higher in patients with systemic vasculitis [median 68.20, IQ (38.25~158.78) (pg/ml)] compared to essential hypertension [median 43.86, IQ (23.30-60.71) (pg/ml)] (p = 0.003) and the healthy volunteers [median 30.76, IQ (9.30-54.16) (pg/ml)] (p < 0.001)." (PMID 33997033, 2021). "Detailed analysis of cell subpopulations revealed a unique microglial subset expressing CD11b/c, CD163, and CD86 exclusively in early hypertension." (PMID 38115109, 2023). "Here, increased CD163+ macrophage population in the mesenteric artery adventitia is associated with decreased sympathetic nerve function, suggesting that macrophages may mediate vascular dysfunction in distinct ways during IBD versus hypertension and other cardiovascular diseases." (PMID 37342800, 2023). "We found a significant correlation between CD163 levels in SAT and key parameters, including visceral fat mass, glycemia, HbA1c levels, T2D, and hypertension." (PMID 37792298, 2023). "In this study, the expression of CD163 and CD206 in peripheral blood monocytes and the concentrations of IL-10 and TNF-α in the serum of patients with hypertension and healthy participants were detected." (PMID 33879070, 2021). "At the late stage of hypertension, we observed a negative correlation between microglial soma size and CD163 in the cortex indicative for a shift towards morphological features that facilitates microglial surveillance contributing to tissue repair." (PMID 38115109, 2023). "Meanwhile, we found that C5AR1, CCL4L2, CCL4, CCL20, CD163, CXCL3, and CXCL12 were only expressed in disease a, suggesting the recruitment of inflammatory factors and promotion of the inflammatory response were both more obvious in hypertension-induced AD." (PMID 35800890, 2022).
Hypertension (continued). "During the early stage of hypertension, we observed negative correlations between CD45 and CD200R and between CD11b/c and CD163 in the cortex, suggesting the involvement of CD45 in downregulation of CD200R signaling pathways and classical activation of microglia." (PMID 38115109, 2023).
malaria (15 papers, 2007 to 2024). Malaria is a serious and sometimes fatal disease caused by a parasite that commonly infects a certain type of mosquito which feeds on humans. "Multivariate logistic regression analysis revealed a significant correlation of risk of severe malaria with both plasma IL-10 and soluble CD163 levels." (PMID 27385484, 2016). "It has been hypothesised that malaria, or other causes of haemolysis, lead to depletion of circulating Hp as it is saturated and taken up by monocytes and macrophages–via CD163." (PMID 17426810, 2007). "Data from our current study indicating an elevated expression of sCD163 by PBMCs from symptomatic malaria patients may explain some of their susceptibility to the disease, as it has been demonstrated that plasma levels of sCD163 are inversely correlated with CD163 expression on monocytes." (PMID 28369062, 2017). "Investigations in children infected with malaria showed increased levels of arginase 1 and IL-10, reduced amounts of NO, and increased expression of M2 markers (CD163, CD206)." (PMID 33330947, 2021). "Previous reports documented an increase CD163 levels in uncomplicated malaria patients as compared to severe malarial anaemia and cerebral malaria patients." (PMID 32414377, 2020). "Higher levels of soluble CD163 and CD25 have been found to be associated with parasitemia in general malaria patients, whereas soluble TNF receptor levels have been associated with parasitemia in pregnant patients." (PMID 31662766, 2019). "In malaria studies, certain receptors and cytokines are commonly investigated, such as CD163, IL-10, and TNF." (PMID 31662766, 2019). "The anti-inflammatory response during malaria also implies the receptor CD163 which scavenges the complex haemoglobin:haptoglobin, allows heme degradation by HO-1, avoids tissue damage, and facilitates IL-10 secretion." (PMID 26385579, 2015). "Furthermore, blood monocytes from malaria patients have increased levels of the monocyte scavenger receptor CD163 and the mannose receptor CD206, and high plasma levels of soluble CD163." (PMID 27385484, 2016). "Few reports have investigated CD163 as a biomarker during malaria, although it may constitute an important factor implied in the anti-inflammatory response." (PMID 26385579, 2015). "However, during malaria episodes, two separate mechanisms affect Hp concentrations, levels of expression and also rate of clearance, affected by Hp phenotype, either due to differences in affinity of Hp to CD163 or rates of receptor mediated endocytosis." (PMID 17426810, 2007). "As measured by flow cytometry gating on monocytes, we found that blood monocytes from children with malaria had significantly higher levels of CD206, and CD163 than did those from HC children." (PMID 27385484, 2016). "Data from other African studies suggest that both malaria and tuberculosis may increase levels of CD163, but our study did not demonstrate that malaria co-infection may significantly influence levels of these markers in acute bacterial infections." (PMID 19675669, 2009). "In these 13 children, CRP, s-TREM-1, CD163 and HMGB1 were higher than in those negative for malaria parasites, but these differences were not significant." (PMID 19675669, 2009).
sarcoidosis (15 papers, 2018 to 2025). Sarcoidosis is a multisystemic disorder of unknown cause characterized by the formation of immune granulomas in involved organs. "In sarcoidosis, an elevated CD11b+ and CD163+ expression seems to contribute towards early M2 polarization." (PMID 35269486, 2022). "In contrast, Shamaei and his colleagues reported enhanced CD163 staining in granulomas of patients with sarcoidosis compared with tuberculous granulomas." (PMID 36685535, 2022). "Elevated expression of M2 macrophage-associated markers have been noted in diseased sarcoidosis tissues, including CD206 and CD163, and their expression correlated with disease severity." (PMID 32849608, 2020). "Immunohistochemical staining for CD163 expression was significantly increased in sarcoidosis sections compared with those from tuberculosis subjects." (PMID 32751786, 2020). "Immunohistochemical comparison of lymph node tissues from patients with tuberculosis and sarcoidosis indicated a notable upregulation of CD163 expression in sarcoidosis cases, implying the involvement of M2 macrophages in the development of sarcoidosis granulomas." (PMID 39904950, 2025). "However, in order to prevent tissue damage to the host and avoid severe immunopathologies, such responses must be controlled by M2-polarized macrophages (CD163+) through the production of anti-inflammatory cytokine mediators, as is common in sarcoidosis." (PMID 39274446, 2024). "This may suggest a correlation between the expression of CD163 and inflammatory status in sarcoidosis patients." (PMID 32760396, 2020). "Currently, blood biomarkers such as ACE, sIL-2R, CD163, CCL18, serum amyloid A, and CRP are employed to aid in the diagnosis and monitoring of sarcoidosis." (PMID 39852350, 2024). "Additional serum biomarkers for sarcoidosis include neopterin, lysozyme, human cartilage glycoprotein-39 (YKL40), CD163, CCL18, serum amyloid A, and C-reactive protein (CRP)." (PMID 39852350, 2024). "Because sarcoidosis is notably associated with Th1/Th17 multisystem abnormity, an increased number of CD68+ CD163− M1 macrophages and CD209+ dendritic cells and a decreased number of CD68+ CD163+ M2 macrophages may be a histologic surrogate for the diagnosis of cardiac sarcoidosis." (PMID 35011991, 2022). "By contrast, in BAL, M1 macrophages (CD40hi cells) were increased in sarcoidosis when compared with other ILD, whereas M2 macrophages (CD163 expressing cells) were similar." (PMID 32751786, 2020). "By contrast, CD163 surface expression, did not vary on MD-macrophages from sarcoidosis and controls exposed to hypoxia (see Figure E3)." (PMID 34456926, 2021).
triple-negative breast carcinoma (15 papers, 2018 to 2026). An invasive breast carcinoma which is negative for expression of estrogen receptor (ER), progesterone receptor (PR), and human epidermal growth factor receptor 2 (HER2). "For example, CD163+ TAMs are predictive of shorter survival in triple-negative breast cancer patients, while spatial distribution patterns provide additional prognostic insights." (PMID 40850976, 2025). "Regarding the duality of TAMs in different tumors, an interesting study conducted with patients diagnosed with triple-negative breast cancer (TNBC) found that TAMs displayed high levels of CD163+ and, therefore, an M2-like phenotype." (PMID 38791312, 2024). "In contrast to previous studies, we observed that higher densities of CD163+ macrophages are independently associated with improved OS and BCSS in women with invasive triple-negative breast cancer." (PMID 38720366, 2024). "Women with triple-negative breast cancer showed significantly improved OS in relation to increased levels of tumor-infiltrating CD163+ macrophages in age-adjusted (Q3 vs. Q1: HR = 0.36; 95% CI 0.16–0.83) and fully adjusted models (Q3 vs. Q1: HR = 0.30; 95% CI 0.12–0.73)." (PMID 38720366, 2024). "Indeed, some authors have described an improved survival of ER- or triple-negative breast cancer (TNBC) patients with a CD163+CD68+ macrophage infiltrate, while others correlated the presence of tumor-infiltrating CD163+ macrophages with a worse prognosis of TNBC patients." (PMID 35309358, 2022).
tuberculosis (15 papers, 2009 to 2025). A chronic, recurrent infection caused by the bacterium Mycobacterium tuberculosis. "CRISPR/Cas9 mediated insertion of NRAMP1 gene for producing tuberculosis resistant cattle, and deletion of CD163 gene for producing porcine reproductive and respiratory syndrome (PRRS) resistant pigs are two groundbreaking applications of genome editing in livestock." (PMID 33260762, 2020). "The CRISPR/Cas9 mediated insertion of NRAMP1 gene for producing tuberculosis resistant cattle and deletion of CD163 gene for producing porcine reproductive and respiratory syndrome (PRRS) resistant pigs are two groundbreaking application of genome editing technique in livestock." (PMID 33260762, 2020). "Higher expression of membrane and soluble CD163 in active tuberculosis patients might provide insights regarding the pathogenesis of tuberculosis, and sCD163 may be a novel biomarker to distinguish TBP from MPE and to predict disease severity." (PMID 31779590, 2019).